MET (MET proto-oncogene, receptor tyrosine kinase)
Diseases named in the same sentence as MET in open-access papers (continued):
Sharing a sentence is not in itself a finding about the gene and the disease.
tumor (continued). "As a result, MET amplification was no longer detectable, and tumor growth continued via alternative oncogenic pathways." (PMID 41268440, 2025). "In keeping with prior work from our group and others on TKI type switching in fusion‐positive tumours, we also showed that the METG1090A mutation, while conferring resistance to type I MET inhibitors, does not affect the binding properties of type II TKIs." (PMID 40437874, 2025). "In addition, activation of the MET signalling pathway, mediated by the receptor tyrosine kinase MET and its ligand hepatocyte growth factor (HGF), enhances neutrophil NO release, which amplifies oxidative stress and promotes tumour cell killing." (PMID 41451221, 2025). "Furthermore, immunohistochemistry (IHC) scores > 2 for both c-MET and AXL were observed in 70% and 90% of tumor specimens, respectively." (PMID 40921965, 2025). "The HGF/c-MET signaling axis contributes to modulating the liver’s microenvironment through various processes, including ECM remodeling, inflammation, angiogenesis, and invasion, to promote tumor progression and metastasis." (PMID 40304568, 2025). "However, our prior work showed that CD24 is essential for tumor growth and metastatic progression in human TNBC cells, as it promotes oncogenic signaling via EGFR and MET." (PMID 40783744, 2025). "Thus, co-treatment with a combination of three inhibitors for EGFR, MET, and FGFR reduces the tumor size of subcutaneous and intracranial GB xenografts in mice to a greater extent than treatment with two inhibitors for EGFR and MET." (PMID 41516252, 2025). "Other somatic mutations associated with VTE independent of tumor type include KRAS, STK11, MET, KEAP1, CTNNB1, and CDKN2B." (PMID 39851266, 2025). "MET signalling acts by phosphorylating various kinases, such as MAPK or PI3K/AKT, thereby modulating the expression of target genes like SLUG, MMP2 and BMP2 involved in motility, invasion, the cell cycle survival and tumour progression." (PMID 39374163, 2025). "Furthermore, pathways involved in tumour invasiveness and metastasis were also connected and presented in pLN+ OSCC, including clusters named ‘MET promotes cell motility’ and ‘SMAD2/SMAD3:SMAD4 heterotrimer regulates transcription’." (PMID 40038875, 2025). "IHC analysis, in mice receiving daily HIF-1α siRNA injections has confirmed the macroscopic image of reduction of tumor volume through the decreased levels of HIF-1α transcriptional targets, like VEGF, GLUT–1, c-MET, and CA-IX and markers for cell growth like MIB-1 and MVD." (PMID 39055895, 2024). "Notably, MET and EGFR share a downstream signaling pathway, indicating that these receptors collaborate to enhance tumor cell proliferation, movement, invasion, malformation, angiogenesis, metastasis, and resistance to chemotherapy (CT)." (PMID 39170944, 2024). "PTK6 may collaborate with a range of growth factor receptors, including as the ERBB family, IGF1R, and MET, as well as a variety of signaling pathways, such as hypoxia, p27/CDK/Cyclins, ERK1/2/P38 to promote tumor progression." (PMID 38573548, 2024). "Additional evidence of the involvement of MET in the landscape of drug resistance is supported by a study conducted by Min and colleagues, which demonstrated that MET signaling activation is essential for GBM stem cells and that METet inhibition suppresses tumor growth and invasiveness." (PMID 38334610, 2024). "Heterodimers of MET with EGFR, HER2, HER3, or RET exhibit distinct roles in tumor development." (PMID 39201787, 2024). "MET’s interaction with its ligand, hepatocyte growth factor/scatter factor (HGF/SF), is particularly critical in promoting the epithelial to mesenchymal transition (EMT), which enhances tumor cell proliferation, motility, and anchorage-independent growth." (PMID 39449330, 2024).
tumor (continued). "Furthermore, the larger tumor size and the lack of evident EMT in the HE cell xenografts, along with the consistent presence of MET in the HM cell xenografts, suggest a distinct role of EMT and MET in tumor progression." (PMID 39256881, 2024). "Mechanistically, when c-MET is amplified or overexpressed, it can bypass EGFR pathway inhibition through the ERBB3 receptor-mediated PI3K/AKT and Grb2/MAPK pathways, thereby maintaining tumor cell growth and survival." (PMID 39201787, 2024). "Importantly, ADAMTSL5 confers tumorigenicity by upregulating oncogenic inputs (i.e., MET, EGFR, PDGFRβ, IGF1Rβ, FGFR4), and its abrogation increases sensitivity of tumor cells to clinically relevant drugs." (PMID 38495872, 2024). "On the other hand, findings suggest that high c-MET activity, reflected in elevated HGF levels, may contribute to an immunosuppressive tumor microenvironment that hampers the efficacy of PD-1/PD-L1 blockade." (PMID 39664377, 2024). "First clinical evidence of MET exon 14 skipping tumours responding to a MET TKI was obtained in studies using crizotinib, an ATP-binding competitor of anaplastic lymphoma kinase (ALK), c-ros oncogene 1 (ROS1), RON, and MET." (PMID 38652103, 2024). "Furthermore, the integration of CD47 blockade, MET inhibitors, and anti-CTLA-4 therapy engages both the innate and adaptive immune systems, enhancing phagocytosis, reducing tumor growth, and strengthening immune responses." (PMID 39275127, 2024). "This review explores the biological functions of the HGF/c-MET signaling pathway in both normal and cancerous cells, examining its multifaceted roles in the NSCLC tumor microenvironment, including tumor cell proliferation, migration and invasion, angiogenesis, and immune evasion." (PMID 39201787, 2024). "Of note, the four responders included in the DSP study, had no MET gene alteration detected on their tumor comprehensive genomic profiling, which was performed as part of a SOC testing at a CLIA-certified lab before trial enrollment." (PMID 38378868, 2024). "Analysis of single-cell RNA transcriptomics suggested that the tumor cells dramatically upregulated EGFR and MET in response to PD-L1 immunotherapy, potentially creating a metabolic state fit for tumor persistence in the tumor microenvironment (TME) and rendered pembrolizumab ineffective." (PMID 38916448, 2024). "Irregular MET activity has been outlined to induce chemoresistance in various cancers and in the maintenance of refractory cancer stem cells, and downregulation of the c-MET/HGF pathway has been reported to reduce cancer stemness and overall tumor growth." (PMID 39458991, 2024). "However, a phase I study combining dacomitinib (a pan-HER inhibitor) with crizotinib (a small-molecule kinase inhibitor of MET and other RTKs) in advanced NSCLC patients showed limited success due to toxicity and modest tumor response." (PMID 39769452, 2024). "Similarly, high levels of MET expression were observed in gastric and NSCLC cancer models that drive tumor growth and metastasis." (PMID 39458991, 2024). "Additionally, amivantamab enhances immune-mediated tumor cell destruction by inducing Fc-mediated phagocytosis and natural killer cell cytotoxicity against cells expressing EGFR and c-MET." (PMID 38892105, 2024). "MET and VEGFR signaling pathways are often co-activated in cancers and may work synergistically to promote tumor growth and resistance to therapy." (PMID 39769452, 2024). "The discoveries of tumor-driver genes such as epidermal growth factor receptor (EGFR), anaplastic lymphoma kinase (ALK), mesenchymal-epithelial transition (MET), and c-ros oncogene 1 (ROS1) in NSCLC have recommended TKIs as the first-line option for patients with advanced stage disease." (PMID 38927911, 2024). "Therefore, activation of the HGF-MET and GAS6-AXL pathways promotes tumor survival, proliferation, infiltration, and metastasis, and blocking VEGF can lead to MET and AXL activation." (PMID 38289361, 2024).
tumor (continued). "This analysis also showed that the maturation of the PTPRZ1–MET protein to the β chain in the tumor samples is similar to that of amplified MET, if not less efficient." (PMID 38254850, 2024). "Additionally, targeting of MET similarly to other RTKs, such as EGFR, IGF1R, and VEGFR, increases tumor cytotoxicity to DDAs." (PMID 38957115, 2024). "Targeting a MET fusion gene with crizotinib in one pHGG patient resulted in a partial response with rapid tumor relapse, yet no lasting response after MET inhibition has been demonstrated for MET-driven pHGGs so far." (PMID 38849845, 2024). "The combination of c-MET inhibition and immunotherapy also augmented the count and functionality of antigen-specific CD8+ T cells within tumor tissues, highlighting its potential impact on the tumor microenvironment." (PMID 39664377, 2024). "Notably, MET and AXL (both known to be involved in the survival, proliferation, infiltration, and metastasis of tumor cells as well as in the mechanisms of tumor resistance to molecularly targeted agents) were reported to be overexpressed in RCC." (PMID 38289361, 2024). "Both c-MET and TGF-β independently and cooperatively suppress anti-tumor immunity." (PMID 39664377, 2024). "We found that tumor cells but not Iba1high TAMs that resided in tumor cell-free adjacent stroma showed activation of MET, however, MET was also activated in the absence of adjacent microglia in some tumor cells, suggesting a paracrine effect of HGF." (PMID 38386085, 2024). "PDX tumors with response to osimertinib and savolitinib combination exhibited strong phospho-MET expression throughout the tumor (quantified by H-score) whereas PDX without response had overall low phospho-MET expression." (PMID 38276867, 2024). "Preliminary clinical data on the injection of MET CAR T cells into breast cancer tumors demonstrated favorable tolerability and induced necrosis, hemorrhage, and inflammatory cell infiltration within the tumor." (PMID 39201787, 2024). "Additionally, responders to cabozantinib plus durvalumab showed features suggestive of preexisting active anti-tumor immune responses, tumor upregulation of VEGF and MET signaling as well as ECM activity and cell adhesion signatures." (PMID 38378868, 2024). "In our analysis, the receptors MET and MST1R displayed increased mRNA expression in tumor samples." (PMID 38212428, 2024). "Moreover, we report differences in oncogene expression such as MYC, MET and BRAF between ROS1+ tumor samples and cell lines, which should be taken into account when interpreting in vitro experiments." (PMID 39737401, 2024). "The CE-IVD IdyllaTM GeneFusion Assay (Biocartis, Mechelen, Belgium) is an RNA-based fully automated RT-PCR assay, designed to concurrently detect presence of ALK, ROS1, RET fusions and MET exon 14 skipping in formalin-fixed, paraffin-embedded (FFPE) tumor tissue sections." (PMID 38492039, 2024). "It was found that a threshold level of c-MET expression in sensitive tumor cells, but not in normal cells, is necessary for significant ABBV-399-mediated tumor cell killing." (PMID 39664377, 2024). "In epithelial cells, MET-HGF/SF interactions activate downstream proteins like Gab1, initiating signaling cascades, such as Shp2, PI3K, and Crk, which induce cellular responses necessary for normal and tumor cell growth." (PMID 39449330, 2024). "Particular attention is given to possible future approaches, including circulating tumor DNA (ctDNA) for therapeutic monitoring, new targeting agents against molecular pathways such as fibroblast growth factor receptor (FGFR) and MET, chimeric antigen receptor (CAR)-T cells, and cancer vaccines." (PMID 39123420, 2024). "Furthermore, the mRNA expression levels of FAM83A, LY6D, MET, MUC16, MYEOV, and WNT7A were elevated in PAAD tissues, while the protein expression patterns of LY6D, MET, MUC16, and WNT7A were higher in tumor sample." (PMID 38169540, 2024).
tumor (continued). "More importantly, the level of MET expression in the PDX tumor did not correlate with the drug treatment regimen." (PMID 39041204, 2024). "The combination of a c-MET inhibitor and the EGF-R inhibitor erlotinib was used compared to using either inhibitor alone in the NSCLC tumor xenograft mice model and indicated a significant anti-tumor function." (PMID 37568193, 2023). "The present study demonstrated that HER3 and MET were not directly associated with each other in CRC but cooperated for the cellular and tumor growth of CRC." (PMID 36751113, 2023). "MET-CAR.CD28ζ TGFP−Luc cell expansion started to decrease 14 days after injection due to the lack of antigen stimulation resulted from tumor regression." (PMID 37779207, 2023). "Moreover, MET exon 14 depletion by employing CRISPR editing technology leads to the enhanced cell migration, tumor invasion, and tumor metastasis through the HGF/MET axis in NSCLC." (PMID 38188023, 2023). "The HGF/MET pathway has gained increasing interest in recent years for its involvement in cell growth, survival, epithelial–mesenchymal transition (EMT), metastasis, stemness, and chemoresistance in several tumor types." (PMID 37887325, 2023). "In addition, in this tumor, the authors observed a high correlation between EGFR and MET (Rho = 0.698, p = 2.31 × 10−26)." (PMID 37370859, 2023). "Based on c-MET expression in pre-treatment tumor tissue, patients were stratified into two groups: no expression of c-MET (group A) and expression of c-MET (group B)." (PMID 38132404, 2023). "Previous studies showed that the MYH9 protein could act as a promoter of tumor stemness that facilitates tumor pathogenesis through the regulation of Wnt-β-catenin-STAT3 signaling, which can further interact with the MET pathway." (PMID 36612298, 2023). "In vitro, tepotinib inhibits MET in a concentration-dependent manner irrespective of the mode of MET activation, and in vivo, tepotinib exhibits marked, dose-dependent antitumor activity in MET-dependent tumor models of various cancer indications." (PMID 36999986, 2023). "In vitro, it inhibited tumor cell proliferation, survival and migration/invasion in cell lines where c-MET is activated by different mechanisms, including c-MET gene amplification, HGF/c-MET autocrine loop formation and c-MET overexpression." (PMID 36839989, 2023). "In agreement with this hypothesis, the transcripts of MET and ERBB3 kinases are decreased in the Kmt2c KO tumours compared to the controls." (PMID 36933062, 2023). "Additionally, MET expression is induced by inhibition of VEGF/VEGFR signaling, and MET signaling promotes angiogenesis in VEGFR inhibitor-resistant tumors, implying that dual inhibition of MET and VEGFR coordinately inhibits tumor angiogenesis." (PMID 37258621, 2023). "These tumours also had similar detection rates for EGFR mutations and for RET, ROS1, ALK and MET oncogenic isoforms compared with tumours in never-smokers, which suggests that they have a similar aetiology and pathogenesis." (PMID 37046096, 2023). "The present results demonstrated that HER3 and MET were not directly associated with each other in CRC but cooperated for the cellular and tumor growth of CRC." (PMID 36751113, 2023). "MET, GPI, ANGPTL4, HSPA5, TGFA, MIF, and ARTN were significantly up-regulated in tumor samples." (PMID 36447119, 2023).
tumor (continued). "A one-time tail-vein injection of MET-CAR.CD28ζ T cells (5 × 106 cells) induced tumor regression after day 14 and significantly inhibited MHCC97H orthotopic tumor growth in 4 out of 7 mice for 90 days while control mice were sacrificed on day 29 due to tumor progression." (PMID 37779207, 2023). "MET is activated by auto-phosphorylation when bound by HGF engaging several downstream signaling networks, including the PI3K/AKT/mTOR, phospholipase C (PLC), and RAS/MAPK/RAF/ERK pathways involved in tumor growth and invasion." (PMID 36831657, 2023). "MET is thought to be a negative prognostic factor, and tumour tissues after sorafenib therapy have increased overexpression of MET." (PMID 35711496, 2022). "MET-targeted therapies using repurposed inhibitors have met with some initial success in the clinic; however, unlike cancers driven by other oncogenes such as EGFR, response rates in METΔex14 mutant tumours are lower." (PMID 35326531, 2022). "Importantly, EGFR, MET, EPHA2, MAPK1, MAPK3, and RPS6 kinase pathways were strongly dependent on FLCN in RPTEC and also strongly respond to FLCN reconstitution in this BHD tumor cell line, as highlighted in the UOK257 INKA rankings in orange." (PMID 35863698, 2022). "On the contrary, T cells would increase protein processing in endoplasmic reticulum and estrogen signaling pathway during advanced stage of tumor PTC10, which promotes primary tumor growth and distant metastasis and increase the expression of MET proto-oncogene." (PMID 36523593, 2022). "In light of the crucial role of MET in metastatic outgrowth, the potential to effectively target the MET process at sites of metastasis or to block the initial EMT stages that allow the dissemination offers new hope for inhibiting metastatic tumor formation." (PMID 35565186, 2022). "One month after removal of the LUAD, expression of MET, PLTP and MFAP5 all decreased, which could be attributed to the radical tumor removal." (PMID 36544145, 2022). "miR-27b could inhibit the proliferation of DLBCL cells and promote the apoptosis of the cells by targeting MET and inhibiting the MET/PI3K/AKT pathway, thus inhibiting tumor progression." (PMID 36502446, 2022). "The survival of tumor-bearing mice was shortened via PTK2 and c-MET overexpression." (PMID 36109787, 2022). "First, in the preclinical study, the tumor cell lines we used had high MET mRNA and/or protein overexpression levels, and we did not investigate the effect of CT053PTSA on models with MET mutations." (PMID 36341335, 2022). "Radiofrequency ablation (RFA) of intrahepatic tumors induces distant tumor growth through activation of interleukin 6/signal transducer and activator of transcription 3 (STAT3)/hepatocyte growth factor (HGF)/tyrosine-protein kinase Met (c-MET) pathway." (PMID 35857766, 2022). "Since a previous study demonstrated that MET is a key transcriptional target gene of MACC1 in multiple cancers and contributes to tumor progression, we wanted to determine whether MACC1 plays a critical role in PC metastasis via MET." (PMID 36333284, 2022). "Cabozantinib is active against both c-MET and VEGFR-2 and could be considered in future trials recruiting patients diagnosed with EOC where their tumour manifests co-localisation of c-MET/VEGFR-2." (PMID 35144591, 2022). "Moreover, the expression of the c-MET protein in the membrane and cytoplasm of PRCC tumor cells was further investigated, as a result, a strong MET expression exists." (PMID 36627997, 2022). "Recent discoveries pointed out that these neoplasms, with a clinical course that differs from their pediatric and adult counterparts, carry specific molecular alterations, namely kinase (ALK, NTRK1/2/3, ROS1, or MET) gene fusions." (PMID 35565372, 2022). "Although some tumor-agnostic gene alterations, including changes in NTRK and MET, lead to precision medicine, the incidences of these genes are low (2–4% for NTRK and 2% for MET)." (PMID 35954337, 2022).